NOTCH3 (notch receptor 3)
Diseases named in the same sentence as NOTCH3 in open-access papers (continued):
Sharing a sentence is not in itself a finding about the gene and the disease.
cancer (continued). "Mutations in PTPRD, CREBBP, BRAF, NOTCH3, TERT, and SETD2, which are involved in various aspects of immune regulation, were reported as potential biomarkers in cancer patients after immunotherapy with improved survival." (PMID 36092890, 2022). "Independent predictors for cancer-specific mortality were NOTCH3 expression and high stage (p < 0.001)." (PMID 35073251, 2022). "Differential Notch3 activation was also evident from co-culture of SNFT with other EOC cell lines and ascites-derived cancer-associated fibroblasts of HGSOC patients expressing varying levels of Jagged1." (PMID 35884426, 2022). "The Notch signaling members are critical in the regulation of CSCs, among which Notch3 overexpression in cancer cells can result in expansion of CSCs and increase platinum resistance." (PMID 34277625, 2021). "Overall, this review provides comprehensive information on the role of Notch3 signaling in cancer and its value as a therapeutic target." (PMID 34195229, 2021). "Notch3 was mainly expressed in the cytoplasm of cancer cells as detected by immunohistochemistry, and the expression of Notch3 in solid adenocarcinoma was significantly higher than that in lepidic adenocarcinoma." (PMID 35118116, 2021). "In this review, we mainly focus on discussing the molecular mechanisms by which Notch3 modulates cancer stemness and chemoresistance, as well as other cancer behaviors including metastasis and angiogenesis." (PMID 34195229, 2021). "As a population of self-renewing cells with high tumorigenic potency, CSCs are found to be activated by Notch3 signaling in several kinds of cancer and contribute to cancer progression through complex mechanisms (See Notch3 and Cancer Stem Cell Properties)." (PMID 34195229, 2021). "Nuclear orphan receptor NR2F6 was upregulated in resistant EOC, which leads to sustain expression of Notch3 signaling in Cancer Stem Cells, leading to acquisition of resistant phenotype." (PMID 33968932, 2021). "One of the important signaling pathways of cancer cell metastasis is the NOTCH3 pathway, which is one of the main angiogenesis actors, but this gene works in many other ways and can facilitate the invasion of cancer cells." (PMID 34054953, 2021). "NOTCH3 expression was detected in the cytoplasm and nucleus of the cancer cells in both intestinal and diffuse-type GC samples." (PMID 33452458, 2021). "Both NR2F6 knockdown, GSI, and Notch3 knockdown helped to overcome cisplatin resistance in NR2F6-overexpressing cancer stem cells." (PMID 34680255, 2021). "The activation of Notch3 signaling is closely related to the activation of cancer stem cells (CSCs), a small subpopulation in cancer that is responsible for cancer progression." (PMID 34195229, 2021). "Among all cancer types in the TCGA database, OC has the highest Notch3 amplification rate (11.64%, 68 of 584 cases)." (PMID 34195229, 2021). "In detail, the KD genes were enriched in terms related to apoptosis-associated functions, such as “Apoptosis”, “Programmed cell death”, “Apoptosis-related network due to altered Notch3 in cancer”, and “Apoptosis-induced DNA fragmentation”." (PMID 33902514, 2021). "Correlations between expression of c‐MET and resistance to cisplatin and ionizing radiations in several types of cancer, or between NOTCH3 expression and enhanced cisplatin resistance, are good illustrations of their implications." (PMID 34542930, 2021). "What’s more, we propose potential treatment strategies to block Notch3 signaling, such as non-coding RNAs, antibodies and antibody-drug conjugates, providing a comprehensive reference for research on precise targeted cancer therapy." (PMID 34195229, 2021). "Cancer cells having high Notch3 showed increased resistance to drug, which upon silencing (N3 siRNA) leads to gemcitabine-induced apoptosis." (PMID 33968932, 2021).
cancer (continued). "ERα+ breast tumor xenografts (with a constitutive active Raf-1/MAPK signaling) developed spontaneous lung metastases, by driving the clonal expansion of those cancer cells by expressing NOTCH3." (PMID 32796631, 2020). "The significant anti-tumorigenic effect caused by the disruption of a single enhancer, i.e., disruption of the NOTCH3 enhancer, stresses that enhancer dysregulation plays a critical role in the biological characteristics of cancers." (PMID 33219226, 2020). "CAIX is thought to be involved in promoting survival and enhancing the invasive behavior of cancer cells via the IL-6/Notch-3/CAIX axis." (PMID 32707920, 2020). "As NRF2-activated cancer cells are capable of highly efficient drug extrusion, targeting NOTCH3 is further advantageous in that it enables the circumvention of NRF2-mediated chemo-resistance." (PMID 33219226, 2020). "Most of the NRF2-positive cases, which are regarded as NRF2-activated cancers, were NOTCH3-positive, which was again consistent with our observation that NOTCH3 is a downstream effector of NRF2 in NRF2-activated NSCLC cell lines." (PMID 33219226, 2020). "qRT‐PCR analysis reflected the much lower NOTCH3 expression in normal tissues than in cancer tissues." (PMID 32343052, 2020). "Expecting therapeutic efficacy improvement, we combined NOTCH3 enhancer inhibition targeting TICs and cytotoxic anti-cancer drugs, such as cis-dichlorodiammineplatinum (CDDP), targeting the proliferating population." (PMID 33219226, 2020). "In HNSCC cells, inhibition of NOTCH3 decreases cell proliferation as well as the sphere forming ability, which is related to cancer stem cells." (PMID 32796631, 2020). "Expression of OCT-3/4, NANOG, SOX2, and Notch receptor 3 (NOTCH3) were increased in the cancer stem cells to promote drug resistance." (PMID 32178477, 2020). "NRF2 directly upregulates NOTCH3 mRNA expression, and both NRF2- and NOTCH3-positive cancers show poor prognosis." (PMID 33375248, 2020). "Enhanced cancer cell growth rates and invasiveness in an IL-6-dependent manner (through activation of Notch-3, Jagged-1, and CAIX via STAT-3) was reported by Studebaker." (PMID 32707920, 2020). "It has been reported that high NOTCH1 and NOTCH3 expression levels are related to poor OS rates in cancer." (PMID 33479597, 2020). "This convergence of cancer-related pathways with the Notch pathway provides additional mechanism whereby Notch3 can contribute to the proliferation and survival of pulmonary vascular cells in PAH." (PMID 31868216, 2019). "Our results provide a strong rationale for brivanib evaluation combined with Notch3 inhibitors in the treatment Notch3-driven cancers." (PMID 30765875, 2019). "Clinical impact of de-regulated Notch-1 and Notch-3 in the development and progression of HPV-associated different histological subtypes of precancerous and cancerous lesions of human uterine cervix was studied." (PMID 31417656, 2019). "Blocking antibodies against Dll4, Notch1, Notch2, or Notch3 are already being tested in phase I clinical trials in cancer patients." (PMID 31191522, 2019). "Several studies demonstrate that Notch3 expression renders cancer cells more resistant to carboplatin, contributing to chemoresistance and poor survival of OC-bearing patients." (PMID 30723507, 2019). "COMP expression leads to a larger cancer stem cell population in vitro and in vivo, as a result of Notch3 pathway activation." (PMID 31737569, 2019). "Notch3 silencing in MCF7 and TFK1 cells results in Mdh1, Idh1 and Ido1 down-representation, as observed in HepG2 and Huh7 HCC cell lines, suggesting that Notch3 regulation of metabolic pathways is a common feature in different human cancer cells." (PMID 30765875, 2019). "Given some limitations of existing drugs blocking Notch signaling, it is important to get new insights into the biology of Notch3 to further stimulate the development of Notch-targeted therapies in cancer." (PMID 29643474, 2018).
cancer (continued). "NOTCH2 was slightly upregulated in three of the analyzed cancer cell lines as compared to control, while NOTCH3 and NOTCH4 were variable and low expressed in PTC cell lines TPC1 and BCPAP." (PMID 30158530, 2018). "The role of BORIS as a chromatin regulator protein was confirmed by its ability to bind in NOTCH3 promoter and increasing the H3K4me3/H3K27me3 ratio leading to abnormal upregulation of NOTCH3 in cancer cells." (PMID 30323717, 2018). "Conversely, the cancer cell expression of Notch3 was very heterogeneous between patients but also within the same patient." (PMID 28719575, 2017). "In comparison with gamma-secretase inhibitor (GSI) in the treatment of paclitaxel in paclitaxel-resistant cancer cells, Notch3 siRNA specific inhibition showed more efficacy." (PMID 28415574, 2017). "We herein report that miR-150 directly targets Notch3, which has been reported by many authors including us to be an oncogene related with chemoresistance and cancer stem cell activation in many human cancers." (PMID 29069826, 2017). "In colorectal cancer, AST-IV inhibits the growth of cancer cells with no cytotoxicity in normal colonic cells, and increases the chemosensitivity of cancer cells to cisplatin through inhibition of NOTCH3." (PMID 29344421, 2017). "Notch3 has been shown to be overexpressed in several types of cancers, which makes it a promising therapeutic target for cancer treatment." (PMID 28415631, 2017). "Notch3 signaling also induced the expression of Cdc42- and Rac1-specific guanine nucleotide exchange factor Asef in cancer cells." (PMID 29104587, 2017). "We showed here that Jag-1 expression by cancer cells was important to limit the dependence receptor function of Notch3." (PMID 28719575, 2017). "This study demonstrated that Notch3 promotes cancer and is regulated by the level of protein acetylation in urothelial cancer cells." (PMID 28416766, 2017). "SCC showed the strongest Notch3 expression in the cancer cells, however, only a small fraction of patients showed nuclear expression (4/10 for SCC and 2/11 for ADC)." (PMID 28719575, 2017). "Notch1 and Notch3 expression is positively correlated with that of PlexinD1 in patient cancer samples." (PMID 27749937, 2016). "To further characterize the NOTCH3 positive fibroblasts, we conducted immunohistochemical staining for α-SMA, which is a marker of cancer associated fibroblasts (CAFs)." (PMID 27124156, 2016). "Through a ROS-independent, lysosome-mediated pathway, NAC counteracts Notch3 malignant signaling in cancer cells." (PMID 27102435, 2016). "Other studies evidenced the importance of Notch signaling in the establishment of BCCs bone metastases, elucidating the role of osteoblast-derived TGF-β1 in Notch3 signaling activation in cancer cells." (PMID 27571063, 2016). "Immunohistochemical analysis using surgically excised OSCC samples showed that NOTCH3-positive CAFs were located not only close to the periphery of cancer nests but also at some distance from the cancer nests." (PMID 27124156, 2016). "Immunofluorescent staining of this co-culture showed a CD31-positive meshwork formed by HUVECs and NOTCH3-positive NHDFs around the cancer cell nests." (PMID 27124156, 2016). "Immunohistochemical and morphometric analysis using human OSCC samples demonstrated that NOTCH3 expression in CAFs significantly correlated with micro-vessel density in cancer stroma." (PMID 27124156, 2016). "NAC suppresses the malignant phenotypes including proliferation, migration and invasion through inhibition of Notch3 signaling in cancer cells." (PMID 27102435, 2016). "Notch3, a type of Notch receptor (Notch1, Notch2, Notch3, and Notch4), plays an important role in promoting ovarian tumorigenesis, cancer progression, and chemotherapy resistance via activating the PI3K/Akt/mTOR signaling pathway." (PMID 27445438, 2016).
cancer (continued). "As ascites is a key finding in cancer, we analyzed the relationship between the coexpression of Notch3 and pS6 expression and the presence of ascites." (PMID 27445438, 2016). "Our study demonstrated that NOTCH3 induction in fibroblasts needs cell-to-cell contact between cancer cells and fibroblasts." (PMID 27124156, 2016). "In summary, NAC reduces Notch3 levels through lysosome-dependent protein degradation, thereby negatively regulates Notch3 malignant signaling in cancer cells." (PMID 27102435, 2016). "Interaction of HIF-1α and Notch3, which is required for the expression of the hypoxia-responsive gene Carbonic Anhydrase 9, is a potential target for cancer/stem cell therapy." (PMID 25749383, 2015). "When we compared Notch3 levels between benign and malignant cell lines, this phenomenon greatly influenced the outcome: If RWPE-1 was included in the analysis, we observed an overall lower expression of Notch3 in cancer." (PMID 25864518, 2015). "Nonetheless, it is of future interest to confirm the synergism in other Notch3-activated cancer cells and in pre-clinical and clinical settings." (PMID 25010594, 2014). "Of note, a growing body of evidence in recent years has indicated that Notch3 is also involved in the regulation of cancer development and progression." (PMID 24919811, 2014). "To this end, we have previously performed a systems biology approach using ChIP-chip and transcriptome analyses to identify Notch3 direct target genes in cancer cells." (PMID 25356737, 2014). "It has been established that Notch3 plays a fundamental role in a variety of cellular functions including cellular differentiation, organ development, and cancer pathogenesis." (PMID 25356737, 2014). "Wild-type WWP2 but not ligase-deficient mutant WWP2 increases mono-ubiquitination of the membrane-tethered Notch3 fragment, therefore attenuating Notch3 pathway activity in cancer cells and leading to cell cycle arrest." (PMID 25356737, 2014). "B-ALL stroma express JAG1, JAG2, and DLL1, and these ligands are responsible for the synergistic activation of cancer cells that expressed Notch3 and Notch4, which ultimately support B-ALL cell survival." (PMID 25309874, 2014). "For example, reagents upregulating the expression of WWP2 and gene therapy approach by re-introducing WWP2 into cancer cells are worth pursuing for the treatment of cancers that have developed dependence on Notch3 signaling." (PMID 25356737, 2014). "The Notch3 signaling pathway is thought to play a critical role in cancer development, as evidenced by the Notch3 amplification and rearrangement observed in human cancers." (PMID 25356737, 2014). "In this context, JAG1 seems to play a central role in linking various pathways, involving well-established cancer-related molecules such as Notch3, interleukin-6 (IL-6), carbonic anhydrase IX (CAIX), and NF-κB." (PMID 25309874, 2014). "We have shown that WWP2 directly interacts with and mono-ubiquitinates post-secretase cleaved Notch3 fragments, promoting their sorting to and degradation in lysosomes, thereby suppressing Notch3 signaling activity in cancer cells." (PMID 25356737, 2014). "The negative regulation of WWP2 on Notch signaling activity is more prominent in Notch3-overexpressing cancer cells." (PMID 25356737, 2014). "The results from this study provide new insights into how Notch3 signaling contributes to cancer development, and should have implications for the design of Notch3-based cancer therapy." (PMID 25356737, 2014). "Higher levels of both Notch1 and Notch3 RNA expression in the cancer cell lines than that in the Het-1A cell line were repeatedly verified." (PMID 23409141, 2013). "We proved that combination of sorafenib and Notch3 depletion significantly decreased both CD31 staining and VEGFR2 in vivo suggesting that Notch3 signaling by cancer cells plays a role in neo-angiogenesis." (PMID 24113128, 2013).
cancer (continued). "The majority of studies consider that Notch1 is involved in cancer promotion and, compared with Notch1, there are a small number of studies regarding Notch3." (PMID 23420695, 2013). "Compared to the Het-1A cells, higher levels of Nocth1 and Notch3 expression in the cancer cell lines were identified." (PMID 23409141, 2013). "Increased expression levels of NOTCH3 correspond with significantly higher recurrence rates of cancer in affected patients and a shorter disease-free periods." (PMID 23528888, 2013). "Overexpression of miR-206 in HeLA cancer cells increases apoptosis by inhibiting Notch3 protein expression and such over- expression plays a major role in PAH." (PMID 23071643, 2012). "The biological significance of a Jagged1/Notch3 positive auto-regulatory loop in cancer cells is open to question." (PMID 20953350, 2010). "Role of circRNAs in the regulation of NOTCH 3 expression in cancers." (PMID 40761890, 2025). "For instance, cancer-associated fibroblast (CAF)-derived Jagged1 activates Notch signaling in tumors, whereas hypoxia-induced crosstalk between Notch3 and the G-protein coupled estrogen receptor (GPER) can antagonize therapeutic responses in estrogen receptor-positive breast cancer." (PMID 41050674, 2025). "This may be due to NOTCH3+ CAFs enhancing vessel sprouting as NOTCH3 expression in CAFs significantly correlates with micro‐vessel density in the cancer stroma." (PMID 39928309, 2025). "Additionally, the ac4C modification of NOTCH3 mRNA was determined to be a vital regulatory switch for its function in the spread of cancer." (PMID 41316475, 2025). "In summary, although we have provided initial insights into the relationship between WWTR1-AS1 and miR-136 and have shown that the lncRNA WWTR1-AS1 upregulates Notch3 through miR-136 to enhance cancer cell stemness in CSCC, further evidence is required to hold the reliability of our findings." (PMID 38331752, 2024). "The difference in NOTCH3 expression levels of different cancer types may be related to the data collection methods and potential biological characteristics." (PMID 38906903, 2024). "The correlation between CNV and expression levels of FGA and NOTCH3 varied across cancers." (PMID 39130639, 2024). "CNV and methylation analyses revealed specific changes in FGA and NOTCH3 across 20 cancers types." (PMID 39130639, 2024). "As a family member of NOTCH family, NOTCH3 also mainly exerts oncogenic roles in cancers." (PMID 38950346, 2024). "In cytological experiments, we found that AAK1 could promote cancer progression and glutamine metabolism via activating the Notch3 pathway in OV cells." (PMID 38169546, 2024). "After suppressing endogenous NOTCH3 levels in MCF-7 cells, the morphology of MCF-7 cells was changed with obvious pseudopodia stretching out, which indicated that suppressing NOTCH3 expression might enhance the invasion and motility of cancer cells." (PMID 38164285, 2024). "COMP also promotes cancer cell stemness by increasing the interaction between Notch3 and its ligand Jagged1, resulting in increased activation of Jagged1-Notch3 signaling and cross-reactivity with other important cancer-related pathways, such as AKT and β-catenin." (PMID 38965233, 2024). "However, WWTR1-AS1 reduced the effects of miR-136 on the expression of Notch3 and cancer cell stemness." (PMID 38331752, 2024). "Our study demonstrated that miR-136 could also target Notch3 to decrease cancer cell stemness in CSCC." (PMID 38331752, 2024). "Research indicates that inhibiting NF-κB signaling may intersect with the NOTCH3 pathway in cancer progrerssion." (PMID 39130639, 2024). "Similar to uLMS, NOTCH3 and NOTCH4 have been implicated in various cancers." (PMID 38927890, 2024).